SPDEF (SAM pointed domain containing ETS transcription factor)
Diseases named in the same sentence as SPDEF in open-access papers (continued):
Sharing a sentence is not in itself a finding about the gene and the disease.
tumor (continued). "Strikingly, the transcriptional regulator SPDEF was recently shown to act as a tumor metastasis suppressor in vivo and the multifactorial adaptor protein MAD2L2 (also known as MAD2B) was proposed to be involved in the TCF4-mediated epithelial-mesenchymal transdifferentiation." (PMID 26967245, 2016). "SPDEF regulates mucus secretion, goblet cell differentiation, tumor progression and metastasis." (PMID 25254494, 2014). "Studies using tumor cell lines show that SPDEF affects cell migration and invasion pathways." (PMID 20862312, 2010). "Importantly, Kruskal–Wallis tests with Dunn’s multiple comparisons confirmed statistically significant differences in SPDEF CpG hypomethylation across tumor stages (TS1–TS4) and ISUP grades (G1–G5), with the highest hypomethylation levels observed in TS-4 and G5 (P < 0.0001)." (PMID 40457266, 2025). "Furthermore, genetic knockdown of FASN efficiently reduced SPDEF expression in tumor spheres." (PMID 36809297, 2023). "However, the roles of SPDEF in tumor progression currently remain controversial." (PMID 37633945, 2023). "Notably, the stemness phenotype was further validated using an extreme gradient tumor formation assay in which MCF7 cells with up-regulated SPDEF were most efficient in tumor initiation compared with the control group, as evident by the sizes of the tumors and the growth kinetics of tumors." (PMID 37633945, 2023). "Likewise, KRT17 and SPDEF might be used to discriminate between patients with high and low tumor-load as indicated by the measured primary tumor percentage and cfDNA VAF." (PMID 33761899, 2021). "Moreover, the mRNA of several cell cycle regulatory genes, such as Cdc25b, Cyclin B1, Cyclin A2, Plk1, Cks1, Aurora B, and Topo 2 alpha were decreased in prostates of TRAMP/SPDEF OE mice, a finding consistent with decreased cellular proliferation and decreased tumor sizes." (PMID 25254494, 2014). "Of note, SPDEF, a member of the E26 transformation-specific (ETS) family, exerted the most apparent changes upon C75 treatment of tumor spheres." (PMID 36809297, 2023). "High SPDEF expression was reported to be more common in the luminal type and is positively correlated with the TNM stage, lymphoid nodal status, and tumor invasion, with a poor prognosis in high-expression groups." (PMID 36428562, 2022). "Here, we found that SPDEF suppressed HNSCC cell proliferation, likely due to the effects of the tumor microenvironment or tumor cell stemness, and will be studied in our future work." (PMID 34667150, 2021). "In the favorable ccrcc2_3 subtypes, miR-204-5p was strongly upregulated, predicted long OS, and repressed several targets that are involved in tumor invasiveness and metastasis (MMP3, MMP9, AURKB, FBN2, ITGB4, SPDEF)." (PMID 32915890, 2020). "Several ETS family members have been shown to act as tumor suppressors within the prostate (EHF, SPDEF, ERF, etc)." (PMID 30603056, 2018). "Knockdown of SPDEF in HCC cell lines increased cell proliferation, survival and invasion in vitro and tumour growth and metastasis in vivo." (PMID 30200227, 2018). "SPDEF did not accelerate the growth of tumors in low SPDEF-expressing cancers with basal-like differentiation but accelerated tumor growth in high SPDEF-expressing tumors with classical differentiation." (PMID 40457266, 2025). "SPDEF, TRIM3, HSPB1, SPINT1, EPN3, and LRFN2 were significantly highly expressed in the HER2-positive type than in TNBC (p < 0.05), as the HER2-positive type is reported to have a larger tumor size and higher stage." (PMID 36428562, 2022). "Lower SPDEF mRNA (n = 10, P = 0.021) and protein (n = 34, P < 0.001) levels were observed in tumor tissues compared with the adjacent non-cancerous tissues." (PMID 34667150, 2021). "In addition, high transcript level of SPDEF was positively related to TNM stage, lymphoid nodal status in Luminal A, with tumour invasion in Luminal B, with lymphoid nodal status in HER2+, and even with TNM stage in TNBC." (PMID 34191390, 2021).
tumor (continued). "In addition, our analysis of differential gene expression between Basal and Non-Basal tumor subtypes provides considerable evidence that SPDEF downregulation is a defining molecular feature of the Basal subtype." (PMID 41228349, 2025). "Notably, the expression of SPDEF and TEAD4 showed opposing trends in IV‐stage tumours." (PMID 40318012, 2025). "The function of SPDEF in tumor metastasis in vivo in any system has not been investigated to date." (PMID 40457266, 2025). "Additionally, the genes in the Light-Yellow module include SPDEF, ELAPOR1, C9orf152, PLPP2, and SCGB2A1 and may be involved in several biological processes including tumor immunity and epithelial cell differentiation." (PMID 39596419, 2024). "Therefore, the discrepancies between these findings and those on SPDEF as an oncogene and/or a tumour suppressor have not been resolved." (PMID 34191390, 2021).
cancer (47 papers, 2002 to 2025). A tumor composed of atypical neoplastic, often pleomorphic cells that invade other tissues. "A previous animal study has suggested that the induction of the signature genes FOXA3 or SPDEF, which are enriched in mucin-producing cancers, along with a KRAS mutation in the lung epithelium, is sufficient to develop mucinous lung tumors in transgenic mice." (PMID 34174841, 2021). "SPDEF plays a pivotal role in various biological functions, and while its association with oncogenesis is established, the nuances of its involvement vary across cancer types." (PMID 38520747, 2024). "CDH1 and SPDEF are closely associated with cancer cell metastasis." (PMID 30977227, 2019). "Our findings provide new mechanistic insights into the complex regulation of SPDEF activity linked to cancer metastasis and characterize a previously unidentified SPDEF/CDK11p58/GADD45α/γ pathway that controls SPDEF protein stability and SPDEF-mediated effects on cancer cell migration and invasion." (PMID 26885618, 2016). "In contrast, other reports have suggested oncogenic activity of SPDEF, underscoring the context-dependent nature of SPDEF’s function across and within cancer types." (PMID 41228349, 2025). "The interplay between SPDEF and other TFs, signaling pathways, and microenvironmental cues likely determines the effect of SPDEF on cancer cell behavior." (PMID 38674385, 2024). "SPDEF has a dual role in cancer by potentializing or inhibiting and acting upon features, such as adhesion, migration, invasion, and epithelial–mesenchymal transition (EMT)." (PMID 38674385, 2024). "These diverse functions underscore the significant impact of SPDEF in cancer biology, marking it as a critical component in developing potential treatments." (PMID 38520747, 2024). "In this study, we delineate the pivotal influence of the SPDEF gene on cancer progression, particularly in the context of the PI3K/AKT signaling pathway." (PMID 38520747, 2024). "In vitro, GALNT7 inhibited reversed the enhanced proliferation, migration, invasion capabilities and even the cancer stem-like cell features due to SPDEF overexpression in luminal BC." (PMID 37633945, 2023). "In total, nine inflammation and cancer-associated DEGs were selected to show their changed expression patterns, comprising four up-DEGs (ADM, FSTL3, SPDEF, and SPNS2) and five down-DEGs (TACSTD2, CCL2, EDIL3, FAM20C, and OLFML2A)." (PMID 37953789, 2023). "The second notable finding of this study is that we provided robust evidence for a regulatory role of SPDEF in the maintenance of luminal BC cancer stem cell-like properties." (PMID 37633945, 2023). "Here, we reported the identification of SPDEF which represents a new mechanism of driving cancer stem cell-like properties and tumorigenicity of luminal BC that is mediated by GALNT7." (PMID 37633945, 2023). "We mainly demonstrated that SPDEF transcriptionally activates GALNT7 via directly binding to its promoter to drive cancer stem cell-like properties and tumorigenicity in luminal BC." (PMID 37633945, 2023). "Yet, the mapped genes were highly relevant to PCa etiology and included known cancer drivers LDLRAD4, GMNN, COL1A1, CD38, PTPRN2, GTSE1 and CAMK2N1 in the risk signature and KLK2, AR, KLK3, SPDEF in the relapse signature." (PMID 33845808, 2021). "In cancer literature, the role of SPDEF, known as the prostate‐derived ETS factor, that functions in BC is widely reported." (PMID 34191390, 2021). "The algorithm based on the analysis of ERG, PCA3 and SPDEF showed its advantages in discriminating the high-grade cancer (≥GS7) from low-grade malignancy (GS6) and benign disease than tPSA in CaP screening." (PMID 28938580, 2017). "SPDEF along with KRASG12D induced malignant mucinous lung tumors (tubulopapillary‐like carcinoma; Fig EV3B), while KRASG12D itself induced benign non‐mucinous lung tumors (Fig EV3B)." (PMID 28255028, 2017).
cancer (continued). "Further investigation of the roles of SPDEF in several cancers including androgen-insensitive prostate cancer is required to understand the mechanism leading to its contradictory effects on cell proliferation." (PMID 27853318, 2016). "While enhanced SPDEF expression blocks migration and invasion, knockdown of SPDEF expression enhances migration, invasion, and metastasis of cancer cells." (PMID 26885618, 2016). "A key role for SPDEF in cancer cell migration, invasion and metastasis has emerged, although with opposite conclusions in different cancer types." (PMID 26885618, 2016). "In contrast, CDK11p58 overexpression induced cancer cell migration and invasion, while re-expression of SPDEF or GADD45α, which we demonstrate here to bind CDK11p58 and inhibit its kinase activity, reduced migration and invasion." (PMID 26885618, 2016). "In contrast, knockdown of CDK11p58 protein expression by interfering RNA or SPDEF overexpression inhibit migration and invasion of cancer cells." (PMID 26885618, 2016). "As shown, these miRNAs are active regulators of the expression of several cancer-related mRNAs, including ZEB1, ZEB2, VIM, VEGFA, NTRK3 and SPDEF, and most of the miRNAs are cancer-related." (PMID 24512620, 2014). "Re-expression of Foxm1 restored cellular proliferation in the SPDEF-positive cancer cells and rescued progression of SPDEF-positive tumors in mouse prostates." (PMID 25254494, 2014). "Using publicly available profiling data, we found that 83% of GATA6-regulated genes are also regulated by SPDEF, and that proliferation/cancer is the function most likely to be modulated by this overlapping gene set." (PMID 24472151, 2014). "Our findings of an underexpressed miR-510 and overexpression of SPDEF in HGSC support an interaction also in this cancer subgroup." (PMID 24512620, 2014). "While previous studies have suggested the role of SPDEF in various tumors, its unique role in specific cancer manifestations remains unclear." (PMID 38520747, 2024). "Although we found that SPDEF might enhance cancer stem cell-like phenotype and tumorigenesis of luminal BC by activating GALNT7 transcription, there are still some limitations to the current study." (PMID 37633945, 2023). "Since SPDEF is a transcription co-activator, it may promote liminal BC cells cancer stem cell-like properties and in vivo cancer biology characteristics by transcriptional activation of genes that are regulators of CSCs." (PMID 37633945, 2023). "This study demonstrated for the first time that SPDEF may promote cancer stem-like features and tumorigenicity in luminal BC, which will add new perspectives to the previously proposed oncogenic activity of SPDEF." (PMID 37633945, 2023). "Meanwhile, the direct targeting of GALNT7 by SPDEF was confirmed by restoration of GALNT7 in SPDEF silenced luminal BC cells which successfully reversed the cancer stem cell-like phenotype and oncogenic function in vitro and in vivo, and the other direction is also true." (PMID 37633945, 2023). "SPDEF has a complex correlation with the prognosis of cancer patients." (PMID 35983409, 2022). "Therefore, we performed a functional knockdown screen of 92 cancer associated transcription factors and identified GATA3, SPDEF, IRF9, and YY1 as candidate transcriptional activators/repressors for APOBEC3B gene expression." (PMID 32934779, 2020). "Mutations in SPDEF are rare in human cancers, with the majority of mutations being non-recurring missense mutations." (PMID 30200227, 2018). "We show that CDK11p58-induced SPDEF degradation reduces expression of the epithelial-specific genes E-cadherin and cytokeratin 18 indicating the CDK11p58-SPDEF axis may play an important role in cancer cell migration and invasion." (PMID 26885618, 2016). "Additionally, GADD45's role in the regulation of CDK11p58 mediating SPDEF degradation introduces a novel activity of GADD45 in cancer cell migration and invasion." (PMID 26885618, 2016).
cancer (continued). "Currently, the role of SPDEF in cancer pathogenesis remains controversial." (PMID 25254494, 2014). "The downregulation of SPDEF in NAL-M may stimulate the migration of cancer cells." (PMID 32754579, 2020). "Although the roles of SPDEF and the PI3K/AKT signaling pathway in cancer are recognized, their specific interaction in PAAD remains incompletely explored." (PMID 38520747, 2024). "Although chronic SPDEF and FOXM1 can promote or inhibit cancer, cyclic FOXM1 activation has recently been shown to increase the lifespan of mice." (PMID 37644339, 2024). "Critically, reduced S100A16 expression mitigated the SPDEF overexpression-induced enhancement of PAAD cell proliferation, underscoring its influence on cancer cell dynamics." (PMID 38520747, 2024). "Altogether, our data indicate that overexpression of SPDEF decreased proliferation of TRAMP C2 and MycCap cancer cells and inhibited prostate carcinogenesis in the orthotopic model." (PMID 25254494, 2014). "Additionally, the potential interplay between SPDEF, S100A16, and the PI3K/AKT signaling pathway is of considerable interest given the significance of this pathway in various cancers." (PMID 38520747, 2024). "Interestingly, SPDEF binds to the promoter of FOXM1, which in a feedback loop is involved in cancer." (PMID 37644339, 2024). "SPDEF (SAM Pointed Domain Containing ETS Transcription Factor), also called prostate-derived ETS factor (PDEF), has a vital function not only in normal cell development but also in cancer development." (PMID 38674385, 2024). "Nevertheless, the role of SPDEF in regulating cancer stem-like properties in luminal BC has not been established prior to the present study." (PMID 37633945, 2023). "For instance, while MITF, SPDEF, CNOT7, BTK, PAF1, and PAX5 seem to be novel key regulators in the context of HPV-induced carcinogenesis, they are apparently already known to play essential roles in other cancer entities." (PMID 30918060, 2019). "We identified potential novel upstream regulators (e.g., CNOT7, SPDEF, MITF, and PAX5) controlling distinct clusters of genes within the HPV-host cell network as well as distinct factors (e.g., CPPED1, LCP1, and TAGLN) with essential functions in cancer." (PMID 30918060, 2019). "SPDEF expression and activation is tightly regulated in cancer cells; however, the precise mechanism of SPDEF regulation has not been explored in detail." (PMID 26885618, 2016). "While we have demonstrated interaction of SPDEF with the androgen receptor (AR) and various other proteins relevant for cancer signalling, no studies have been reported as of yet about the precise regulatory mechanisms of SPDEF protein expression and activity in the context of metastasis." (PMID 26885618, 2016). "WA activation of the transcription factor SPDEF (SAM pointed domain containing ETS transcription factor) shows the highest relevance in MDA-MB-231 cells, a finding which is in line with the inhibitory role of SPDEF in migration and invasion in several types of cancer." (PMID 24498382, 2014). "These genes included AGR2, KRT17, SPDEF, and LAD1 which were expressed in EV-RNA of patients 5 and 15 and of all cancer cell lines, but not in HBDs." (PMID 33761899, 2021).
infection (4 papers, 2014 to 2023). The state of being infected such as from the introduction of a foreign agent such as serum, vaccine, antigenic substance or organism. "Since TRAMP C2 cells do not express endogenous SPDEF, we expressed SPDEF by lentiviral infection (left panel SPDEF OE)." (PMID 25254494, 2014). "At MOI 1 or 5 for HRV-A16, we found that gene expression of SPDEF, FOXA3, and AGR2 were significantly increased in ALI-PBEC at 48 h post-infection." (PMID 32637364, 2020). "Additional DEX induced transcription factors, SPDEF (Sam-pointed domain containing Ets transcription factor), Krüppel-like transcription factor 15 (KLF15), KLF4, KLF6, and GATA6, stimulate productive infection and certain key viral promoters." (PMID 31134079, 2019).
prostate (1 paper, 2014). "Nevertheless, the controversy regarding the role of SPDEF in prostate carcinogenesis remains unresolved." (PMID 25254494, 2014). "In summary, decreased expression of SPDEF in prostate epithelial cells was sufficient to increase prostate carcinogenesis, while increased SPDEF inhibited prostate carcinogenesis induced by SV40 T antigens." (PMID 25254494, 2014). "To determine the role of SPDEF during prostate carcinogenesis in vivo, we crossed SPDEF−/− mice with transgenic TRAMP mice that express SV40 T large and small antigens under the control of probasin promoter to drive oncogenic transformation of prostate epithelial cells." (PMID 25254494, 2014).
SPDEF also shares sentences with these, for which no sentence is quoted: invasive breast carcinoma (3 papers); brain cancer (2); colitis (2); colorectal tumor (2); acute myeloid leukemia (1); adenocarcinoma (1); allergic asthma (1); chronic obstructive pulmonary disease (1); ciliopathies (1); Diamond-Blackfan anemia (1); glioblastoma (1); invasive ductal carcinoma (1); kidney damage (1); lymphoma (1); macular oedema (1); Meckel syndrome (1); metastatic disease (1); oral squamous cell carcinoma (1); pancreatic adenocarcinoma (1); pancreatic ductal adenocarcinoma (1); preeclampsia (1).